IL37 (interleukin 37)
Diseases named in the same sentence as IL37 in open-access papers (continued):
Sharing a sentence is not in itself a finding about the gene and the disease.
sarcopenia (6 papers, 2021 to 2026). Progressive decline in muscle mass due to aging which results in decreased functional capacity of muscles. "Results indicating that rehabilitation-associated improvement in the parameters used to monitor sarcopenia correlated with a significant reduction of IL-37 led us to investigate the post-transcription miRNA-mediated mechanism involved in IL-37 production, including miR-657 and miR-335-3p." (PMID 33902634, 2021). "Thus, IL-37 may be used as biomarker to monitor the rehabilitation-associated improvement, and as therapeutic targets in sarcopenia." (PMID 34248996, 2021). "The authors suggested that IL-37 and its regulatory miRNAs could be used as biomarkers in patients with sarcopenia." (PMID 35053303, 2022). "Successful rehabilitation for sarcopenia results in a reduction significant of CRP (p=0.04) as well as of IL-18 (p=0.008) and IL-37 (p=0.009) concentration." (PMID 34248996, 2021). "In the acute sarcopenia cohort, while plasma IL-18 did not change in response to surgery, plasma IL-37 was significantly increased in post-surgery plasma samples compared to the pre-surgery samples." (PMID 41592067, 2026). "Efficient rehabilitation programs for sarcopenia, thus, could reduce inflammation and the need for IL-37 to exert its negative feedback to control the release of inflammatory cytokines." (PMID 33902634, 2021).
gastric cancer (5 papers, 2020 to 2024). A primary or metastatic malignant neoplasm involving the stomach. "Elevated circulating IL-37 levels have also been reported in several types of cancers (e.g. epithelial ovarian cancer, gastric cancer), and chronic heart failure, and were associated with poor prognosis." (PMID 34367169, 2021). "A protective role of IL-37 during the development of gastric cancer has been demonstrated, where the processed form of IL-37 binds to SMAD-3, relocates to the nucleus, and hinders the transcription of various pro-inflammatory genes." (PMID 39206201, 2024). "It was reported the elevated serum levels of interleukin-37 was correlated with poor prognosis in gastric cancer." (PMID 33489865, 2020). "The trend of serum IL-37 level in PDAC seems discrepancy in gastric cancer and epithelial ovarian cancer." (PMID 32226541, 2020). "The comparison of the observations in CRC and gastric cancer appear contradictory, since IL-37 is an anti-inflammatory cytokine, whereas IL-34 is a pro-inflammatory cytokine, yet these two cytokines both provide a protective role during the development of cancer within the gastrointestinal system." (PMID 35186997, 2022). "On the other hand, elevated levels of IL-37 observed in gastric cancer patients align with reduced host immunity at the cellular and humoral levels, indicating that IL-37 may contribute to the development of gastric cancer via suppressing pro-inflammatory responses." (PMID 39206201, 2024). "There is at least a partial explanation that IL-37 inhibits immunosurveillance, although these data are not specific for gastric cancer, they are a more general immunological observation." (PMID 39206201, 2024). "In addition, it remains to be clarified whether the suppression of IL-37 or IL-34 in CRC and gastric cancer, respectively, results in or from different stimuli, which requires further investigation." (PMID 35186997, 2022). "Elevated levels of IL-37 observed in gastric cancer patients align with reduced host immunity at the cellular and humoral levels, indicating that IL-37 may not play a protective role in gastric cancer." (PMID 39206201, 2024).
ischemia (5 papers, 2017 to 2022). A hypoperfusion of the BLOOD through an organ or tissue caused by a PATHOLOGIC CONSTRICTION or obstruction of its BLOOD VESSELS, or an absence of BLOOD CIRCULATION. "Furthermore, IL-37 might have a treatment function for ACS via inhibition of ROCK activation, according to our observation that IL-37 reversed the increased ROCK activity in cultured PMBCs after ischemia/reperfusion injury or the ROCK stimulus." (PMID 28039466, 2017). "Highly concentration of the anti-inflammatory interleukin-37 exerted a protective effect by suppressing the activated Rho Kinase (ROCK) activity in the peripheral blood mononuclear cells in vivo and in vitro after ischemia/reperfusion injury and stimulation of the Rho activator, calpeptin." (PMID 28039466, 2017).
ischemic stroke (5 papers, 2017 to 2022). A stroke disorder caused by obstruction of blood flow to the brain, due to thrombotic (local blood clot formation) or embolic (due to a blood clot or other material traveling from another site) event. "Large randomized controlled trials are needed to further verify the role of IL-37 in ischemic stroke." (PMID 35173738, 2022). "We found that in the first 3 days after ischemic stroke in 55 patients, the plasma abundance of IL-37 was ~2-fold higher than in 24 controls." (PMID 31061403, 2019). "Here we assessed the effect of ischemic stroke in humans on the regulation of IL-37 in blood and the post-mortem brain." (PMID 31061403, 2019). "First, ischemic stroke resulted in a marked increase in plasma IL-37 in both humans and IL-37tg mice." (PMID 31061403, 2019). "Our study shows a rather stable elevation of IL-37 levels post-ischemic stroke, which (if compared to available data from other studies) is three to ten times elevated after acute ischemic stroke with an uptrend noted in the first few days." (PMID 29234571, 2017). "The study shows a rather stable early elevation of serum IL-37 levels post-ischemic stroke." (PMID 29234571, 2017). "This study aimed to measure urine and serum IL-37 levels in patients with ischemic stroke." (PMID 29234571, 2017). "Serum IL-37 levels were in the range of 44 - 5,235 in patients with ischemic stroke." (PMID 29234571, 2017). "In addition, future studies can also analyze whether the IL-37 variant is also associated with the severity of CAD and other diseases such as ischemic stroke associated with inflammation." (PMID 28181534, 2017). "Immunohistochemical analysis of post-mortem human brain sections obtained from a person who died after ischemic stroke indicated IL-37-expressing cells accumulating within the infarct but not in the non-ischemic hemisphere." (PMID 31061403, 2019). "Similarly, in IL-37tg mice subjected to ischemic stroke, plasma IL-37 was ~8-fold higher than in sham-operated IL-37tg mice 24 h after surgery (P < 0.001; note that WT mice do not express IL-37)." (PMID 31061403, 2019).
myasthenia gravis (5 papers, 2020 to 2025). Myasthenia gravis (MG) is a rare, clinically heterogeneous, autoimmune disorder of the neuromuscular junction characterized by fatigable weakness of voluntary muscles. "Compared with healthy controls, the levels of IL-37 in the serum and PBMCs were significantly decreased in patients with myasthenia gravis (MG)." (PMID 40583347, 2025). "Along the same line, patients affected by myasthenia gravis (MG) presented lower IL-37 serum levels compared with healthy controls, which were associated with high follicular T helper and B cell numbers." (PMID 35211118, 2022). "Similarly, Liu’s study also proved that IL-37 directly inhibited the proliferation and cytokine production by Tfh cells in Myasthenia Gravis." (PMID 40427088, 2025).
pneumonia (5 papers, 2019 to 2025). An acute, acute and chronic, or chronic inflammation focally or diffusely affecting the lung parenchyma, caused by an infection in one or both of the lungs (by bacteria, viruses, fungi, or mycoplasma.). "This study investigated the role of the anti‐inflammatory factor IL‐37 in Omicron variant infection‐induced pneumonia using a SARS‐CoV‐2 Omicron‐infected BALB/c mouse model." (PMID 40452816, 2025). "A study revealed that the protective effects of IL-37 is associated to the increased expression of IL-10 in mice with acute pneumonia." (PMID 34248996, 2021). "This study demonstrates that IL-37 treatment can ameliorate influenza pneumonia by attenuating cytokine production, especially by macrophages." (PMID 31736917, 2019). "Thus, IL-37 ameliorates influenza pneumonia by the reduction of cytokine production, especially by macrophages, in a MAPK-dependent manner." (PMID 34248996, 2021). "Thus, IL-37 might serve as a promising new target for the treatment of influenza A-induced pneumonia." (PMID 31736917, 2019). "Another strategy is the administration of interleukin-37 (IL-37), a member of IL-1 family, which is able to reduce the MyD88/NLRP3-IL-1/IL-6 pathway, ameliorating pneumonia, viral myocarditis (through Th17/regulatory T cell immune response), and other infectious diseases." (PMID 33182653, 2020). "Thus, in the present study, we focused on IL-37 treatment in H1N1-infected mice, to investigate the therapeutic effect and the mechanisms by which IL-37 treatment ameliorates influenza pneumonia." (PMID 31736917, 2019).
rheumatic diseases (5 papers, 2020 to 2025). "For example, IL-37, a member of the IL-1 family which is stimulated by SARS-CoV-2, has been shown to suppress IL-1β, IL-6, TNFα and CCL2 in rheumatic diseases by acting on mTOR and enhancing the AMPK activity, to maintain mitochondrial membrane potential and limit the toxic effects of ROS." (PMID 36389723, 2022).
tuberculosis (5 papers, 2015 to 2025). A chronic, recurrent infection caused by the bacterium Mycobacterium tuberculosis. "The study was aimed to assess IL-18, IL-18 binding protein (IL-18BP), IL-18R, IFN-γ, and IL-37 mRNA expression in patients with active tuberculosis (ATB) and healthy volunteers with latent M.tb-infection (LTB) or M.tb-uninfected healthy controls (Control)." (PMID 32521630, 2020). "Serum IL-37 was positively correlated with IL-10 and negatively correlated with IL-12 in patients with tuberculosis." (PMID 26435567, 2015). "In patients with active tuberculosis (ATB), serum levels of IL-37 are elevated." (PMID 41293155, 2025). "Interleukin-37 (IL-37), a novel member of the IL-1 family, plays fundamental immunosuppressive roles by broadly reducing both innate inflammation and acquired immunity, but whether it is involved in the pathogenesis of tuberculosis (TB) has not been clearly elucidated." (PMID 28076390, 2017).
viral myocarditis (5 papers, 2018 to 2023). Myocarditis that is caused by an infection with a viral agent. "Our study aims to verify the potential effects and underlying mechanisms of IL-37 in Coxsackievirus B3 (CVB3)-induced viral myocarditis (VMC)." (PMID 36418383, 2022). "Echocardiography showed that IL-37 treatment resulted in better cardiac function parameters in mice with viral myocarditis, including LVEF (P < 0.05), LVFS (P < 0.05), IVSs (P < 0.01) and IVSd (P < 0.01)." (PMID 36418383, 2022). "Our previous studies has confirmed that recombinant human IL-37 alleviates CVB3-induced viral myocarditis by regulating the ratio of Th17/Treg cells." (PMID 36418383, 2022). "In this study, our findings indicate activated pyroptosis in viral myocarditis and we have confirmed that IL-37 significantly inhibits the activation of NLRP3 inflammasome caused by CVB3." (PMID 36418383, 2022). "In CVB3-induced viral myocarditis, IL-37 treatment obviously weakened the upregulation of NLRP3 inflammasomes (NLRP3, ASC, and caspase-1), and the activation of NLRP3 inflammasomes as evidenced by decreased inflammatory mediators (IL-1β and IL-18)." (PMID 36418383, 2022). "These pathological roles of Th17 cells in viral myocarditis make them a potential therapeutic target, and the addition of Th17-inhibiting factors such as IL-27, IL-35, IL-37, and progranulin has already been shown to reduce myocarditis in mouse models." (PMID 34696354, 2021). "The beneficial effects of Tregs on viral myocarditis make them potential therapeutic targets, and factors that stimulate Tregs such as IL-37 and thrombospondin-2 have been shown to ameliorate myocarditis in animal models." (PMID 34696354, 2021). "In viral myocarditis, IL-37's inhibition of NF-κB signaling pathway may be an important means to inhibit the expression of a variety of pro-inflammatory genes." (PMID 36418383, 2022). "Although the relationship between these signal channels and the mechanism by which IL-37 affects fibrous tissue deposition still need further study, the current results have suggested that IL-37 has an important potential as a treatment for viral myocarditis." (PMID 36418383, 2022). "However, in viral myocarditis, the effects of IL-37 on NLRP3, pyrolysis, IL-1R8, etc. remain unclear." (PMID 36418383, 2022). "Therefore, we speculated that IL-37 can improve viral myocarditis by inhibiting the activation of NLRP3 inflammasome-mediated pyroptosis." (PMID 36418383, 2022). "However, whether IL-37 has an effect on viral myocarditis caused by CVB3 has not been reported yet." (PMID 36418383, 2022).
Alzheimer disease (4 papers, 2021 to 2025). A progressive, neurodegenerative disease characterized by loss of function and death of nerve cells in several areas of the brain leading to loss of cognitive function such as memory and language. "Indeed, the results reported here demonstrate that expression of an anti-inflammatory IL-37 cytokine is able to reduce neuroinflammation and cognitive decline in a mouse model of Alzheimer’s disease." (PMID 36040311, 2022). "In addition, we crossed the hIL-37tg mouse with an animal model of Alzheimer’s disease (APP/PS1) to investigate the anti-inflammatory properties of IL-37 under chronic neuroinflammatory conditions." (PMID 36040311, 2022). "Similarly, in the mouse model of Alzheimer’s disease (AD), IL-37 attenuates microglial activation." (PMID 40332510, 2025). "In summary, during chronic neuroinflammation associated with Alzheimer’s disease, a significant deficit in synaptic plasticity (functional LTP and structural spine density) was documented, whereas rescue was observed in transgenic AD animals overexpressing the anti-inflammatory cytokine IL-37." (PMID 36040311, 2022).
aspergillosis (4 papers, 2014 to 2025). Aspergillosis is an infection, growth, or allergic response caused by the Aspergillus fungus. "To directly prove this, we assessed NLRP3-deficient mice for susceptibility to aspergillosis and the effects of IL-37 administration." (PMID 25375146, 2014). "As a fundamental inhibitor of innate immunity, IL-37 protects against lung injury by inhibiting pro-inflammatory cytokine production in mice with aspergillosis." (PMID 41293155, 2025). "In a mouse model of aspergillosis, IL-37 significantly reduced NLRP3-dependent neutrophil recruitment and IL-1b secretion, attenuating lung inflammation and injury." (PMID 41293155, 2025). "To this purpose, we evaluated the impact of IL-37 on inflammasome activation and inflammation in Tir8−/− mice with aspergillosis." (PMID 25375146, 2014). "IL-10 expression was greatly increased after IL-37 treatment in mice with aspergillosis." (PMID 26435567, 2015). "As uncontrolled IL-1β promotes detrimental neutrophil-dependent inflammation during aspergillosis, we examined whether IL-37 pretreatment affects the level of IL-1β production and inflammasome activation." (PMID 25375146, 2014). "In lung aspergillosis mouse model, compared with untreated aspergillosis mice, expression of NLRP3 mRNA was significantly decreased in mice intraperitoneally injected with IL-37, while levels of myeloperoxidase (Mpo), CxCl2, IL-1β, IL-17A, and IFN-γ were significantly reduced." (PMID 29805973, 2018). "IL-37 markedly reduced NLRP3-dependent neutrophil recruitment and steady state mRNA levels of IL-1β production and mitigated lung inflammation and damage in a relevant clinical model, namely aspergillosis in mice with cystic fibrosis." (PMID 25375146, 2014).
chronic heart failure (4 papers, 2017 to 2022). "In conclusion, our study is the first to investigate the association between plasma IL-37 levels and chronic heart failure." (PMID 28781417, 2017). "We measured plasma IL-37 levels by enzyme-linked immunosorbent assay (ELISA) in 158 patients with chronic heart failure and 30 control subjects." (PMID 28781417, 2017). "Furthermore, to fully assess the role of plasma IL-37 on cardiac inflammation and left ventricular remodeling, future studies are required to examine the underlying mechanism responsible for the increase of plasma IL-37 in patients with chronic heart failure." (PMID 28781417, 2017). "In the present study, we are the first to demonstrate that plasma IL-37 becomes elevated in chronic heart failure patients, indicating a potential role of IL-37 in the development of heart failure." (PMID 28781417, 2017). "Research demonstrates that IL-37 reduces TNF-α and IL-1β cytokine production from human macrophages, is increased in chronic heart failure patients and attenuated the production of inflammatory cytokines in serum or synovial joints in RA, suggesting IL-37 may have a role in clinical disease." (PMID 29686666, 2018).
Cirrhosis (4 papers, 2021 to 2026). A chronic disorder of the liver in which liver tissue becomes scarred and is partially replaced by regenerative nodules and fibrotic tissue resulting in loss of liver function. "Serum IL-37 levels have been found to be higher in patients with cirrhosis compared to healthy controls and positively correlated with cirrhosis stage score." (PMID 39995661, 2025). "The correlation of serum IL-37 with disease severity in cirrhosis suggests its potential as a novel target modulating the course of liver fibrosis." (PMID 33746950, 2021). "In particular, IL-37 may complement AFP for HCC detection in decompensated cirrhosis, where conventional biomarkers often fail." (PMID 42073372, 2026). "Moreover, we demonstrate the correlation of serum IL-37 with disease severity in human cirrhosis." (PMID 33746950, 2021).
coronary artery calcification (4 papers, 2021 to 2024). Calcification of the coronary artery, used as a measure of coronary atherosclerosis, a risk factor for myocardial infarction. "Additionally, patients with coronary artery calcification showed significantly increased plasma IL-37 concentrations, with correlation analysis revealing positive associations between IL-37 levels and age, fasting glucose, alkaline phosphatase, IL-6, TNF, and C-reactive protein." (PMID 39337246, 2024). "For example, some studies found that IL-37 in severe coronary artery calcification elevated markedly." (PMID 34580597, 2021). "In addition, a positive correlation between plasma IL-37 and OPG has been detected in patients with severe coronary artery calcification, suggesting that IL-37 is a potential biomarker of arterial calcification." (PMID 34422917, 2021).
depression (4 papers, 2022 to 2025). "Additionally, IL-37 was reported to be involved in regulating inflammatory processes in relevance to depression." (PMID 38812484, 2024).
experimental autoimmune encephalomyelitis (4 papers, 2010 to 2025). An autoimmune demyelinating disease of the central nervous system that is produced experimentally in animals by the injection of homogenized brain or spinal cord in Freund's adjuvant. "The role of IL-37 in experimental autoimmune encephalomyelitis has been investigated, and recombinant human IL-37 has been confirmed to exert therapeutic effects on the EAE model." (PMID 40583347, 2025). "In the present study, we investigated the anti-inflammatory and therapeutic potential of IL-37 in experimental autoimmune encephalomyelitis (EAE), a mouse model of MS." (PMID 33391457, 2021).
fibrosis (4 papers, 2014 to 2022). the formation of excess fibrous connective tissue in an organ or tissue in a reparative or reactive process. "The aim of this study was to investigate IL-37-affected macrophage polarization in liver granuloma formation and fibrosis in S. japonicum infection." (PMID 36002836, 2022). "We found that IL-37 reduced mucin production and peribronchial fibrosis due to collagen deposition as shown by Masson's trichrome staining and hydroxyprolin content." (PMID 25375146, 2014).